ENSG00000288838 (novel transcript)
Gene: Long non-coding RNA gene on chromosome 9 (62,798,833 to 62,802,715, reverse strand). Ensembl gene ENSG00000288838.
Gene Ontology:
Molecular function: structural constituent of ribosome
Cellular component: ribosome